INS (insulin)
Diseases named in the same sentence as INS in open-access papers (continued):
Sharing a sentence is not in itself a finding about the gene and the disease.
Insulin resistance (continued). "In the current experiments, both Es and EsM transplantation resulted in improvement of insulin resistance, as evidenced by inhibition of serum insulin concentration and HOMA-IR." (PMID 28545248, 2017). "Treatment with the SL extract improved serum glucose, insulin, and hepatic insulin resistance in HFD-fed mice." (PMID 28578672, 2017). "Our study also showed that fasting serum insulin and insulin resistance index (HOMA-IR) values at baseline and after six years were correlated with percent change in FVC." (PMID 28346522, 2017). "Induction of insulin resistance in experimentally aged rats was evidenced by increased blood glycated hemoglobin, brain contents of insulin and receptors for advanced glycated end-products, as well as decreased brain insulin receptor level." (PMID 28832656, 2017). "Insulin resistance is characterized by the failure of insulin to repress the expression of gluconeogenic genes, which was mainly mediated by the Akt signaling pathway." (PMID 28445156, 2017). "Activation of mTORC1 in muscle of obese and high-fat-fed rodents results in p70S6K-mediated feedback inhibition of insulin signaling, which can reduce glucose update by muscle and contribute to systemic insulin resistance." (PMID 28594375, 2017). "Our prospective pilot study of acupuncture affecting insulin sensitivity on polycystic ovary syndrome (PCOS) combined with insulin resistance (IR) showed that acupuncture had a significant effect on improving the insulin sensitivity of PCOS." (PMID 28274268, 2017). "In the present study, we confirmed that intermittent hypoxia induces insulin resistance, characterized by greater fast glycemia, an impaired systemic insulin sensitivity and lower AKT phosphorylation in adipose tissue and liver in our model." (PMID 28255159, 2017). "Progressive insulin resistance was also suggested based on a modest increase of plasma insulin at 4 weeks of intervention vs. a 5-fold elevation to 1.09 ± 0.283 ng/mL at 24 weeks of HFF-feeding." (PMID 29249964, 2017). "An increase in the insulin level and insulin resistance was found in the COMT siRNA-treated mice compared with control mice." (PMID 28801594, 2017). "Type 2 diabetes mellitus (T2DM) is a long-term metabolic disorder characterized by high blood sugar, insulin resistance, and impaired insulin secretion." (PMID 29163370, 2017). "Metformin is an effective treatment for GDM and other disorders of insulin resistance, but often requires additional treatment with insulin in order to maintain adequate glycaemic control." (PMID 28212289, 2017). "It seems that the earliest abnormality to be related to insulin resistance than to defect in insulin secretion." (PMID 29340122, 2017). "These conditions along with insulin resistance, low insulin production, and/or hyperphagia can worsen the situation and lead to hyperglycemia, glucose intolerance, and eventually diabetes." (PMID 28607631, 2017). "Many research showed that HCV infection can induce insulin resistance (IR) in the liver through multiple mechanisms which interferes with insulin signaling pathway both directly and indirectly, inducing the production of several proinflammatory cytokines." (PMID 29285303, 2017). "Studies performed at the cellular level showed that PPARγ activation directly modulated the expression or phosphorylation of specific molecules of insulin signaling cascade to ameliorate insulin resistance." (PMID 28690544, 2017). "In patients with preserved beta-cell function, increased endogenous insulin secretion counter-balances such insulin resistance." (PMID 28497374, 2017). "In type 2 diabetes, the pancreas produces insulin, however, the cells in the body cannot respond to insulin properly; this also referred to as insulin resistance." (PMID 28294968, 2017). "Insulin resistance is a physiological condition, in which cells fail to respond to the normal actions of the hormone insulin, and reduction or impairment of insulin-stimulated glucose uptake." (PMID 28333091, 2017).
Insulin resistance (continued). "More importantly, we provided evidence that SIRT1 knockdown led to cardiac insulin resistance, as low expression of SIRT1 caused reduced IRS2 expression and impaired insulin signaling in both in vivo and in vitro models." (PMID 28883902, 2017). "It has been demonstrated that an increased plasma FFA level seriously affects insulin signaling pathway and contributes to the development of intracellular insulin resistance." (PMID 28184199, 2017). "Noninsulin‐dependent T2DM is caused by both environmental and genetic factors and impairs an individual's ability to regulate blood glucose levels through the inability of insulin to perform properly, which leads to the development of insulin resistance." (PMID 28638713, 2017). "This suggested that the increase of insulin secretion was starting to become inadequate in relation to the degrees of insulin resistance and glucose intolerance was arising." (PMID 28264067, 2017). "Six weeks of Western diet significantly increased fasting plasma glucose and insulin levels, as well as the insulin resistance index (HOMA-IR)." (PMID 28246388, 2017). "Currently the most common clinical method used for the identification of insulin resistance is measuring of the plasma insulin level under fasting conditions." (PMID 29057258, 2017). "In adipocytes, insulin resistance was induced by incubating cells with 25 mM glucose and 100 nM insulin for 24 h." (PMID 28620170, 2017). "The ectopic accumulation of lipids in skeletal muscle has been viewed as a major factor in the etiology of insulin resistance and type 2 diabetes by reducing insulin stimulated glucose uptake." (PMID 28055958, 2017). "Since an index of insulin resistance, Homeostasis Model Assessment of Insulin Resistance (HOMA-IR), is calculated using plasma glucose and insulin levels, the magnitude of insulin resistance has a close relationship with both plasma glucose and insulin levels." (PMID 28715453, 2017). "There was a significant reduction in insulin resistance within the anthocyanins group, but a null change in the placebo group, suggesting the potential ability of these extracts to improve insulin secretion and sensitivity." (PMID 28994705, 2017). "Insulin resistance is defined as a reduced response of target tissues such as skeletal muscle, liver, and adipocytes to insulin." (PMID 28817063, 2017). "More detailed analysis and understanding of the role of miR-195 in diet-induced hepatic insulin resistance can be found in "Saturated fatty acid-induced miR-195 impairs insulin signaling and glycogen metabolism in HepG2 cells"." (PMID 29159212, 2017). "Overexpression of Hsd11b1 in either liver or adipose tissue renders mice insulin resistant, conversely knockout of this gene protects mice from glucocorticoid-induced insulin resistance." (PMID 28443133, 2017). "In sequence, insulin resistance, the impaired secretary insulin and glucose tolerance become true, and the following result is to develop T2DM." (PMID 28333091, 2017). "An abrupt increase in postprandial glucose level induces higher insulin response and eventually results in insulin resistance." (PMID 29026444, 2017). "This study achieved significant improvements in blood glucose and insulin levels, insulin resistance, weight and BMI with the effects sustained over a two-year period." (PMID 29216263, 2017). "This is the first study with the aim to compare the associations of bioactive and immunoreactive leptin levels with selected parameters of insulin secretion and insulin resistance." (PMID 28542631, 2017). "Epidemiological studies have suggested that tea or tea extracts can decrease insulin resistance, with homeostasis model assessment of insulin resistance or insulin sensitivity, TG, glycemic, cholesterol, and lipid profiles as index." (PMID 28531120, 2017). "Insulin resistance impairs glucose tolerance and induces muscle atrophy in type 2 diabetes, and Akt activation is often impaired in insulin-resistant muscle." (PMID 29259227, 2017).
Insulin resistance (continued). "Obesity causes hyperinsulinemia, as the pancreatic β cells produce excess insulin in an attempt to compensate for insulin resistance in peripheral tissues." (PMID 29104232, 2017). "The physiological regulation of insulin secretion, for example by incretins, somatostatin, sulfonylurea and age-related insulin resistance, mainly modulates the amplitude of insulin pulses." (PMID 29118381, 2017). "Offspring who slept ≥8 h also had statistically significantly higher levels of insulin, insulin resistance (HOMA), as well as marginally higher glucose level." (PMID 29276708, 2017). "As GDM and type 2 diabetes mellitus (T2D) share similarities in their pathogenesis with respect to impaired insulin secretion and increased insulin resistance, research efforts focused on mapping their genetic properties." (PMID 28072873, 2017). "In the context of insulin resistance and type 2 diabetes, it is admitted that beta cells are unable to increase insulin output to maintain glucose tolerance and that progressive functional changes precede cell apoptosis." (PMID 28742858, 2017). "Two main classes of antidiabetic drugs, thiazolidinediones (TZDs) and biguanides act by reducing insulin resistance (insulin sensitizers)." (PMID 29184536, 2017). "The increased levels of glycated hemoglobin in diabetic patients reflect a sustained state of insulin resistance, despite the high percentages of subjects being treated with exogenous insulin in these groups." (PMID 28841856, 2017). "Insulin tolerance test (ITT) was used for evaluating insulin resistance, and the efficiency of insulin was quantified by its ability in reducing blood glucose level." (PMID 28333148, 2017). "The levels of insulin and insulin resistance (HOMA-IR) negatively correlated with FVC% predicted, FEV1% predicted, and FEV1/FVC ration in total population and the no-asthma group." (PMID 28916790, 2017). "IFG is largely associated with an impaired insulin secretion and impaired suppression of hepatic glucose output, while IGT is mainly associated with muscle insulin resistance and defective insulin secretion." (PMID 27913943, 2017). "We highlighted in this article the case of T2DM or insulin resistance, in which a reduction of insulin activity led to microvascular alterations (in skin, eye, kidney, and neurovascular tissues, among others)." (PMID 28424632, 2017). "Proper preoperative glucose load can promote early phase insulin secretion, which is an important measure for improving insulin resistance." (PMID 28086896, 2017). "Body weight, glucose, insulin, and the homeostatic model assessment of insulin resistance (HOMA‐IR) were greater in HF compared to Std and HFEX after the 4 week intervention." (PMID 28676551, 2017). "KD-fed mice also had an impaired insulin ability to suppress endogenous glucose production confirming insulin resistance at the level of the liver." (PMID 28534852, 2017). "In fact, male rat offspring of dams that consumed a high-sugar diet had increased serum insulin, leptin, and resistin levels at 21 days of age, which is an early indication of insulin resistance." (PMID 28684678, 2017). "In conditions of obesity and insulin resistance mitochondrial content in this tissue is reduced, while treatment with insulin sensitizing drugs such as thiazolidinediones (TZDs) increase mitochondrial content." (PMID 28404813, 2017). "IGF-1, instead, enhances insulin metabolic and anabolic action, and lower IGF-1 levels have been shown to associate with impaired glucose tolerance, insulin resistance and metabolic syndrome, and to predict T2DM onset." (PMID 28881681, 2017). "MiRNAs have been reported to be involved in insulin sensitivity but information is primarily derived from preclinical cell- and animal models for insulin resistance." (PMID 28983252, 2017).
Insulin resistance (continued). "However, it is plausible to speculate that there may be a synergistic effect of obesity on T2D risk in relation to the SLC30A8 variant, potentially driven by the combined impact of lower insulin secretion and obesity-associated elevations in glucose levels and insulin resistance." (PMID 29093761, 2017). "The insulin resistance of α-cells was proposed as a pathophysiological mechanism, in addition to classical insulin targets, such as liver, skeletal muscles, and adipose tissue." (PMID 28426798, 2017). "Significant improvements were observed in plasma glucose and insulin levels, homeostasis model assessment-insulin resistance (HOMA-IR) and in haematoxylin and eosin-stained liver tissues." (PMID 28770011, 2017). "The Ras-ERK insulin pathway is another cascade of insulin receptor activation, which has been less studied in insulin resistance." (PMID 28587267, 2017). "Hyperglycemia and the development of type 2 diabetes (T2D) depend on environmental components together with genetic factors resulting in insulin resistance in the target tissues and reduced capacity of the pancreatic β‐cells to secrete enough insulin." (PMID 29122960, 2017). "In general, β cells respond to an incremental change in glucose with an incremental change in insulin, and this response moderated with the severity of insulin resistance." (PMID 28199386, 2017). "To evaluate the extent of insulin resistance in our model, we further measured the serum concentration of FFAs and insulin." (PMID 28718838, 2017). "Further in a state of high insulin resistance, the lipogenic action of insulin was suppressed and therefore adipose tissue was reduced." (PMID 28767672, 2017). "Insulin resistance can also develop in cardiovascular tissues where insulin can contribute to the development of CVD, hypertension and metabolic diseases." (PMID 28507343, 2017). "Genetic osteocalcin deletion induced glucose intolerance, increased fat mass, insulin resistance, decreased expression of insulin target genes in liver and muscle, and decreased adiponectin gene expression in adipose tissue." (PMID 28194185, 2017). "In this cross-sectional study, we evaluated the relationships between several kinds of biomarkers and insulin resistance, and insulin secretion in T2DM and healthy controls." (PMID 28654680, 2017). "Memory deficit anda decrease in GLUT4 and hippocampal insulin signaling have been observed inanimal models of insulin resistance." (PMID 29213501, 2017). "The NLRP3 inflammasome activity promotes insulin resistance and genetic deficiency in NLRP3 inflammasome, ASC or caspase-1 ameliorates insulin signaling pathway in obese mice." (PMID 28765650, 2017). "Obesity, insulin resistance, and insulin secretory dysfunction play different roles during each stage of T2D progression." (PMID 28491871, 2017). "One BTS component, Gardenia, improved insulin resistance and repaired insulin signaling via upregulation of P-Akt, glucose transporter 4, and glucose uptake in skeletal muscle of STZ-diabetic mice." (PMID 28360931, 2017). "Insulin is an important mediator of lipid metabolism, and a core feature of insulin resistance is dyslipidemia." (PMID 29163128, 2017). "This study aimed to investigate how factors associated with systemic insulin resistance influence podocyte insulin signalling and, consequently, the development of renal disease in situations of insulin resistance, including diabetic nephropathy." (PMID 28852804, 2017). "Dysfunction of insulin-producing pancreatic islet beta cells and insulin resistance co-exist in T2DM." (PMID 28515792, 2017). "This is consistent with previous research, which suggests a strong link between adiposity, insulin signaling, and the development of insulin resistance." (PMID 28231807, 2017). "Elevated hepatic glucose production is one of the pathophysiological consequences of insulin resistance in the liver, which is the inability of insulin to inhibit hepatic glucose production or gluconeogenesis." (PMID 29362600, 2017).
Insulin resistance (continued). "The insulin resistance comprises both reduced insulin secretion and reduced insulin sensitivity of peripheral organs." (PMID 28453535, 2017). "Conversely, sarcopenia is thought to promote insulin resistance (reduced insulin‐mediated whole‐body glucose disposal) because muscle tissue is the main site responsible for glucose disposal, and sarcopenia promotes physical inactivity." (PMID 28556540, 2017). "DI increased insulin levels, while insulin resistance (HOMA-IR) increased by 43 ± 11% on R0 vs. baseline." (PMID 29081752, 2017). "HFD fed animals presented decreased insulin sensitivity (kITT) when compared to the control group and GK rats showed insulin resistance of greater magnitude." (PMID 29220408, 2017). "On the other hand, insulin resistance inhibits the antilipolytic activity of insulin in the adipose tissue and increases free fatty acids (FFAs) in the serum and liver, leading to mitochondrial dysfunction as well as cardiac fat accumulation." (PMID 28718838, 2017). "Initial oral glucose tolerance testing revealed normal glucose tolerance with elevated insulin levels in all four patients, consistent with moderate to severe insulin resistance, with fasting hyperglycaemia seen in P1 and P4 at 20 and 37 years respectively." (PMID 28414270, 2017). "Insulin resistance index showed that INS and GLP-1 were increased in all the medicated groups after the treatment." (PMID 29254185, 2017). "SYE remarkably improved all the indicators related to insulin resistance, including glucose level, serum insulin level, HOMA-IR, and AUC in both SYE and HFD + SYE groups." (PMID 29085434, 2017). "T2DM consists of an array of dysfunctions characterized by hyperglycemia, which results from insulin resistance, inadequate insulin secretion, and excessive glucagon secretion." (PMID 28521289, 2017). "They found that over-expression of RNase-L in C2C12 mouse myoblast cells enhanced insulin signaling pathway in a palmitate-induced insulin resistance model." (PMID 28399925, 2017). "The botanical test formula significantly improved adipocyte insulin sensitivity, glucose uptake, and in an animal model, prevented the development of insulin resistance and T2DM." (PMID 28679380, 2017). "Insulin resistance is a pathological condition in which cells fail to use insulin effectively, leading to high blood insulin and sugar levels." (PMID 29027980, 2017). "Insulin resistance (IR) is a state that body tissues have less sensitivity to insulin and as a result, downstream metabolic pathways that are regulated by insulin are impaired and blood glucose rises." (PMID 29201096, 2017). "Third, high TT levels, together with insulin and markers of insulin resistance have been demonstrated to increase breast and PCa incidence and worsen prognosis, even in men and women without BRCA mutations." (PMID 29262604, 2017). "Fasting blood samples were collected for assessment of nonesterified fatty acids, tumor necrosis factor-α (TNF-α), interleukin-6 (IL-6), adiponectin, insulin and estimation of insulin resistance (HOMA-IR)." (PMID 28977210, 2017). "The progressive development of insulin resistance during peripartum has been validated through direct measurements of insulin secretion and responsiveness, such as glucose tolerance testing and insulin tolerance testing." (PMID 28486481, 2017). "Because of the whole body insulin resistance observed in the adult offspring, we examined components of the insulin-signaling pathway in these animals." (PMID 28055958, 2017). "On the side, several studies has reported that high uric acid inhibits insulin signaling and induces insulin resistance." (PMID 29262606, 2017). "If a patient with PCOS is treated with metformin, insulin resistance is improved and the serum insulin level is reduced, which suppresses ovarian androgen production." (PMID 29259467, 2017).